MYT1L (myelin transcription factor 1 like)
Description:
Transcription factor that plays a key role in neuronal differentiation by specifically repressing expression of non-neuronal genes during neuron differentiation. In contrast to other transcription repressors that inhibit specific lineages, mediates repression of multiple differentiation programs. Also represses expression of negative regulators of neurogenesis, such as members of the Notch signaling pathway, including HES1. The combination of three transcription factors, ASCL1, POU3F2/BRN2 and MYT1L, is sufficient to reprogram fibroblasts and other somatic cells into induced neuronal (iN) cells in vitro. Directly binds the 5'-AAGTT-3' core motif present on the promoter of target genes and represses transcription by recruiting a multiprotein complex containing SIN3B. The 5'-AAGTT-3' core motif is absent from the promoter of neural genes.
Synonyms: MyT1-L; KIAA1106; NZF1; ZC2HC4B; ZC2H2C2; MRD39
Tractability: PROTAC: its protein half-life has been measured.
Gene: Protein-coding gene on chromosome 2 (1,789,113 to 2,331,664, reverse strand). Ensembl gene ENSG00000186487.
Subcellular location: Nucleus; Chromosome
Subcellular location (Human Protein Atlas): Vesicles
Gene Ontology:
Molecular function: DNA-binding transcription factor activity, RNA polymerase II-specific; DNA-binding transcription repressor activity, RNA polymerase II-specific; cobalt ion binding; DNA binding; DNA-binding transcription activator activity, RNA polymerase II-specific; DNA-binding transcription factor activity; metal ion sequestering activity; retinoic acid-responsive element binding; RNA polymerase II transcription regulatory region sequence-specific DNA binding; transcription coactivator activity; zinc ion binding
Biological process: negative regulation of transcription by RNA polymerase II; nervous system development; neuron development; neuron differentiation; neuron fate commitment; neuron fate specification; regulation of transcription by RNA polymerase II; positive regulation of transcription by RNA polymerase II; regulation of DNA-templated transcription
Cellular component: chromatin; nucleus; chromosome
Genetic constraint (gnomAD): Loss-of-function variants: 4 observed, 107.15 expected, observed/expected ratio (o/e) 0.0373, 90% interval 0.017 to 0.085. The upper end of that interval is the gene's LOEUF score, 0.085, which puts it in group 1 of 6, group 1 being the genes least tolerant of losing a copy. Missense variants: 892 observed, 1,473 expected, observed/expected ratio (o/e) 0.61, 90% interval 0.57 to 0.64. Synonymous variants: 502 observed, 568.46 expected, observed/expected ratio (o/e) 0.88, 90% interval 0.82 to 0.95.
Gene-disease validity (ClinGen):
ClinGen rates the evidence that MYT1L causes each of these diseases.
syndromic complex neurodevelopmental disorder (autosomal dominant): Definitive. A disorder that involves more than one phenotype associated with the central nervous system, including but not limited to intellectual disability, autism, and seizures (epilepsy), and also a distinctive pattern of other features including dysmorphisms and/or congenital malformations.
Homologues: Orthologues: chimpanzee MYT1L (99% identical), macaque MYT1L (99% identical), guinea pig MYT1L (95% identical), mouse Myt1l (95% identical), rabbit MYT1L (94% identical), rat Myt1l (94% identical), dog MYT1L (93% identical), pig MYT1L (90% identical), tropical clawed frog myt1l (86% identical), Caenorhabditis elegans ztf-11 (14% identical), Drosophila melanogaster Pits (7% identical), Caenorhabditis elegans ifbp-1 (5% identical). Paralogues in human: MYT1 (48% identical), ST18 (41% identical), IRF2BPL (10% identical), IRF2BP2 (9% identical), IRF2BP1 (9% identical).
Diseases named in the same sentence as MYT1L in open-access papers:
MYT1L is named in the same sentence as 68 diseases in open-access papers, as found by Europe PMC text mining. Sharing a sentence is not in itself a finding about the gene and the disease. The quoted sentences say what the papers report.
Intellectual disability (19 papers, 2017 to 2025). "In neurodevelopmental disorders, loss-of-function mutations in the MYT1l gene are correlated with intellectual disability, autism spectrum disorder, and obesity." (PMID 41210245, 2025). "MYT1l, a transcription factor important for neural development, is associated with intellectual disability, autism, and obesity." (PMID 40313396, 2025). "Reports in the literature indicate that deletions within MYT1L are usually associated with intellectual disability, and duplications with schizophrenia." (PMID 38539661, 2024). "Mutations in Myt1L in chromosomal band 2p25.3 have been linked to intellectual disability, while Myt1L repetition has been linked to schizophrenia and MMD." (PMID 35468096, 2022). "Several MYT1L mutations have been identified in patients with obesity, intellectual disability, developmental delay, autistic features and behavioral problems." (PMID 32153512, 2020). "Other data indicate the importance of Myt1l in neuronal development: Myt1l overexpression in NSCs and in vivo increases neuronal differentiation and mutations in Myt1l have been associated with intellectual disability, schizophrenia and autism." (PMID 30971887, 2019). "We have identified a new genetic condition caused by MYT1L mutations, further study of this gene will help us understand, and treat, intellectual disability and obesity." (PMID 28859103, 2017). "Given the phenotype of intellectual disability and predisposition to overweight/obesity we reasoned that MYT1L should be expressed in relevant neuroanatomical structures." (PMID 28859103, 2017). "MYT1L mutation could cause neuronal developmental disorders, including intellectual disability, autism, and attention-deficit hyperactivity disorder (ADHD)." (PMID 39083243, 2025). "Moreover, human genetics studies found MYT1L mutations to cause intellectual disability and autism spectrum disorder often coupled with obesity." (PMID 35538503, 2022). "MYT1L mutation can lead to intellectual disability and obesity." (PMID 34026747, 2020). "In the zebrafish there was also reduction of a brain hormone called oxytocin which is involved in thought processes, which may explain why MYT1L mutations cause intellectual disability." (PMID 28859103, 2017). "One additional patient was diagnosed with MYT1L-related developmental delay–intellectual disability–obesity syndrome." (PMID 41009569, 2025). "There has been a report of concomitant diagnosis of FXS with three other genetic conditions such as Duchenne muscular dystrophy (DMD), PPP2R5D-related and MYT1L-related intellectual disability." (PMID 38025430, 2023). "Specifically, MYT1L loss of function (LoF) is associated with intellectual disability (ID) and autism spectrum disorder (ASD), while MYT1L duplication has been observed in patients with schizophrenia (SCZ)." (PMID 35869058, 2022). "In keeping with a role in cognition/intellectual disability, MYT1L is expressed at significantly higher levels in the adult cerebral cortex than in the hippocampus, basal ganglia and hypothalamus (Mann-Whitney U-test, P<0.001)." (PMID 28859103, 2017). "Mutations in the myelin transcription factor 1-like (MYT1L) gene have been associated with obesity following an autosomal dominant mode of inheritance, which is mainly accompanied by developmental and behavioral problems, intellectual disability, and epilepsy." (PMID 38397265, 2024). "Indeed, 98% (50 out of 51) of currently reported cases with heterozygous MYT1L deletion or loss-of-function mutations were diagnosed with ASD and/or intellectual disability." (PMID 36782060, 2023). "Variation in MYT1L is implicated in fibromyalgia and is associated with a non-specific clinical phenotype that includes intellectual disability, early-onset obesity, and speech delay." (PMID 34140969, 2021).
Intellectual disability (continued). "Although our patient did not present with marked developmental delay or intellectual disability, her aggressive behavior, learning difficulties and the early-onset obesity are likely to be related to the identified MYT1L variant." (PMID 32153512, 2020). "MYT1L is a conserved zinc finger transcription factor and mutations have been reported in patients diagnosed with intellectual disability, schizophrenia, epilepsy, and ASD, suggesting that MYT1L-mediated gene regulation may be important in preventing NDDs including ASD." (PMID 36782060, 2023).
Obesity (15 papers, 2014 to 2026). Accumulation of substantial excess body fat. "The patient in this study with the presumed de novo MYT1L variant had severe obesity, aggressive behavior and learning difficulties." (PMID 32153512, 2020). "Our report confirms that CNVs and SNVs of MYT1L are associated with a syndromic presentation consisting of developmental delay/ID, hyperphagia and obesity." (PMID 28859103, 2017). "Here we utilized exome-sequencing data from 4,296 parent-child trios in the Deciphering Developmental Disorders (DDD) study to demonstrate that SNVs in MYT1L are associated with a phenotype resembling that of 2p25.3 deletions with ID and obesity." (PMID 28859103, 2017). "In conclusion, we identify MYT1Lmutations as a cause of syndromic obesity, and establish MYT1L as a member of the leptin-melanocortin-SIM1 pathway, with downstream loss of OXT associated with MYT1L mutations a potential therapeutic target." (PMID 28859103, 2017). "22q11.2 deletion carriers have increased rates of obesity, and the presence of cleft lip/palate, congenital heart disease or parathyroid disease can permit distinction from MYT1L variant carriers." (PMID 28859103, 2017). "This showed that loss of MYT1L in zebrafish causes a problem with the development of the hypothalamus, which may explain how MYT1L mutations cause obesity in humans." (PMID 28859103, 2017). "This study demonstrates that MYT1L variants are associated with syndromic obesity in humans." (PMID 28859103, 2017). "This leads us to hypothesise that MYT1L may play a role in the development of the hypothalamus, and that MYT1L loss of function may be associated with obesity by impairing development of hypothalamic nuclei." (PMID 28859103, 2017). "Given the obesity phenotype in patients with MYT1L SNVs we hypothesized that loss of MYT1L function may interfere with development of the neuroendocrine hypothalamus." (PMID 28859103, 2017). "Here, we discuss the combined functional effects of additional haploinsufficient genes, that may concur with heterozygous deletion of MYT1L, in the aetiology for syndromic obesity associated with 2p25.5 subtelomeric deletion." (PMID 25126114, 2014). "This study shows that Myt1l heterozygous (Het) KO mice recapitulate many phenotypes reminiscent of the human syndrome, including obesity, hyperactivity, and social deficits." (PMID 37100461, 2023). "In summary, our findings in the newly generated mouse model for Myt1l haploinsufficiency are consistent with key elements of the clinical phenotype reported in humans, most notably obesity, hyperactivity, and reduced motor performance." (PMID 35538503, 2022). "By means of our newly generated Myt1l-deficient mouse line, we further provided deeper insights into the role of Myt1l during postnatal development and showed that Myt1l haploinsufficiency led to obesity and multifaceted behavioral alterations in mice." (PMID 35538503, 2022). "Our findings implicate many genes previously associated with obesity (e.g. PTBP2, TMEM18, MYT1L, POU3F2, SIM1, SH2B1), and also identified other potentially relevant candidates including TAS1R3, ALOX5AP, and GAS6." (PMID 29441128, 2018). "Knockdown of MYT1L orthologues in zebrafish resulted in altered hypothalamic oxytocin expression, providing a potential mechanism for the obesity phenotype in humans." (PMID 28859103, 2017). "In summary, we have identified a series of individuals with MYT1L de novo SNVs who present with a syndrome of ID and obesity." (PMID 28859103, 2017). "The expression pattern of MYT1L in human brain also supports a role for the gene in appetite/obesity." (PMID 28859103, 2017). "The clinical presentation of MYT1L CNV and SNV carriers overlaps with other mendelian causes of obesity." (PMID 28859103, 2017).
Obesity (continued). "It seems these developmental impacts of MYT1L haploinsufficiency indicate a well-conserved role for the protein: across two labs, with independently generated lines, MYT1L haploinsufficient mice were also shown to have obesity, hyperactivity, and social deficits." (PMID 35869058, 2022). "Myt1l haploinsufficiency led to obesity and multifaceted behavioral alterations in mice." (PMID 35538503, 2022). "We then hypothesized that MYT1L might be expressed in hypothalamic structures relevant to appetite and obesity during brain development." (PMID 28859103, 2017). "In addition, we identified rare heterozygous missense variants in ADCY3 (p.G1110R), MYT1L (p.R807Q), ISL1 (p.I347F), LRP2 (p.R2479I, and p.N3315S) and a hemizygous missense variant in GRPR (p.L87M) (each in one patient), possibly contributing to the obesity phenotype in these patients." (PMID 32153512, 2020). "Six of the MYT1L SNV carriers were overweight or obese based upon BMI centiles and patient 4 requires a dress size 22, implying obesity." (PMID 28859103, 2017). "Thus, MYT1L CNVs and SNVs may lead to hyperphagic obesity by impairing hypothalamic development." (PMID 28859103, 2017). "We could not demonstrate significant expression of MYT1L in hypothalamic structures relevant to appetite and obesity in the adult brain." (PMID 28859103, 2017).
schizophrenia (15 papers, 2012 to 2025). A major psychotic disorder characterized by abnormalities in the perception or expression of reality. "Mutations in the MYT1l gene are also implicated in schizophrenia and other neuropsychiatric disorders." (PMID 41210245, 2025). "MYT1L-mutant neurons exhibited a decrease in neuronal GO terms and an enrichment of genes implicated in epilepsy, schizophrenia, and ASD among the deregulated genes." (PMID 36782060, 2023). "A case–control study with a relatively large sample size showed that rs17039584 located near 5′ untranslated regions and rs10190125 in intron 1 of MYT1L gene were significantly associated with Schizophrenia." (PMID 24015200, 2013). "Research has demonstrated that microdeletions in MYT1l are significantly associated with childhood-onset schizophrenia, indicating that MYT1l may contribute to the pathogenesis of these conditions." (PMID 41210245, 2025). "Myt1l is also associated with nervousness, depressive disorder and schizophrenia." (PMID 26745496, 2016). "Gene set enrichment analysis (GSEA) highlighted several non-neuronal cell fate signatures among the upregulated genes, and indicated an overall enrichment of genes implicated in epilepsy, schizophrenia, and ASD among the deregulated genes in Myt1l-mutant brains." (PMID 36782060, 2023). "In addition, a number of sex-specific genetic associations with schizophrenia risk have been reported for several genes such as ZNF804A, the myelin transcription factor 1-like (MYT1L), and interferon γ (IFN-γ)." (PMID 31642026, 2020). "Alterations of SNTG2 and MYT1L have been previously reported in patients with ASD and schizophrenia, respectively." (PMID 22346768, 2012). "Childhood-onset schizophrenia abnormalities identified by Addington and Rapoport include 22q11, 45,X atypical/mosaic, 47,XXX, duplications of 16p11.2, MYT1L duplication on chromosome 2, and NRXN1 deletion on chromosome 2." (PMID 22214315, 2012).
autism (10 papers, 2017 to 2025). Persistent deficits in social interaction and communication and interaction as well as a markedly restricted repertoire of activity and interest as well as repetitive patterns of behavior. "Using these translational models, we show that MYT1L deficiency is sufficient to induce autism-associated phenotypes, ranging from deregulation of gene expression and delayed neurogenesis to cortical thinning and altered behaviour." (PMID 36782060, 2023). "Likewise, many neuronal genes with H3K27ac gain and increased expression under CHD2 deficient conditions are linked to the etiology of autism and other NDDs, including MYT1L, NRXN3, SLC12A5, and SNAP25 32–35." (PMID 36115870, 2022). "Interestingly, for each of the genes CIB2, FBRSL1, PACS2, KDM4B, and MYT1L, we found 2 individuals with autism with de novo variants in DAEs interacting with these genes." (PMID 34663447, 2021). "Overall, this indicates that heterozygous deletion of MYT1L during human induced neurogenesis causes deregulation of autism-associated genes and activation of non-neuronal target genes that result in neurogenesis delays at least in part mediated by increased WNT and NOTCH signalling." (PMID 36782060, 2023). "RFX transcription factors bind to a X-box consensus motif, which was found by the authors in some neuronal specific enhancers and/or promoters of autism risk genes (such as AP2S1, KDM6B, ANK2, NONO, and MYT1L)." (PMID 34768579, 2021). "MYT1L is not the only autism related gene to show differential sex effects, so similar experiments should be done in other models (Shank3, Ube3a) to determine how generalizable these gonadal and chromosomal contributions are to neurodevelopmental traits, and with updated FCG mice." (PMID 39966983, 2025).
autism spectrum disorder (7 papers, 2020 to 2025). A spectrum of developmental disorders that includes autism, and Asperger syndrome. "We report a case of MYT1l-related disorder presenting with global developmental delay and features of autism spectrum disorder, associated with the previously documented but functionally uncharacterized c.1695G > T (p.Arg565Ser) variant." (PMID 41210245, 2025). "MYT1L is an autism spectrum disorder (ASD)-associated transcription factor that is expressed in virtually all neurons throughout life." (PMID 36782060, 2023). "We report a case of MYT1l-related MRD39, distinguished by pronounced global developmental delay and autism spectrum disorder, and characterized by a novel c.1695G > T missense variant that has not been previously documented." (PMID 41210245, 2025).